NPR3 (natriuretic peptide receptor 3)
Description:
Receptor for the natriuretic peptide hormones, binding with similar affinities atrial natriuretic peptide NPPA/ANP, brain natriuretic peptide NPPB/BNP, and C-type natriuretic peptide NPPC/CNP. May function as a clearance receptor for NPPA, NPPB and NPPC, regulating their local concentrations and effects. Acts as a regulator of osteoblast differentiation and bone growth by binding to its ligand osteocrin, thereby preventing binding between NPR3/NPR-C and natriuretic peptides, leading to increase cGMP production (By similarity).
Synonyms: ANP-C; ANPR-C; NPR-C; ANPRC; C5orf23; NPRC; GUCY2B; FLJ14054; BOMOS
Tractability: Small molecule: it has a high-quality binding pocket. Antibody: UniProt places it where antibodies can reach, with high confidence; UniProt predicts a signal peptide or a membrane-spanning region; its Gene Ontology location is reachable by antibodies, with medium confidence. PROTAC: ubiquitination databases record sites on it; its protein half-life has been measured; a small molecule that binds it is known. Other modalities: a drug acting on it is in phase 2 or 3 trials.
Target class: Membrane receptor
Gene: Protein-coding gene on chromosome 5 (32,689,070 to 32,791,724, forward strand). Ensembl gene ENSG00000113389.
Subcellular location: Cell membrane
Subcellular location (Human Protein Atlas): Cytosol
Gene Ontology:
Molecular function: chloride ion binding; hormone binding; natriuretic peptide receptor activity; peptide binding; peptide hormone binding; protein binding; protein homodimerization activity; receptor decoy activity; G protein-coupled peptide receptor activity
Biological process: negative regulation of cold-induced thermogenesis; osteoclast proliferation; positive regulation of relaxation of smooth muscle; positive regulation of urine volume; regulation of blood pressure; regulation of osteoblast proliferation; signal transduction; skeletal system development; G protein-coupled receptor signaling pathway
Cellular component: extracellular exosome; plasma membrane; protein-containing complex; membrane
Genetic constraint (gnomAD): Loss-of-function variants: 23 observed, 35.41 expected, observed/expected ratio (o/e) 0.65, 90% interval 0.47 to 0.92. The upper end of that interval is the gene's LOEUF score, 0.92, which puts it in group 3 of 6, group 1 being the genes least tolerant of losing a copy. Missense variants: 534 observed, 571.75 expected, observed/expected ratio (o/e) 0.93, 90% interval 0.87 to 1. Synonymous variants: 242 observed, 242.22 expected, observed/expected ratio (o/e) 1, 90% interval 0.9 to 1.11.
Homologues: Orthologues: chimpanzee NPR3 (99% identical), macaque NPR3 (99% identical), rabbit NPR3 (94% identical), dog NPR3 (94% identical), pig NPR3 (93% identical), rat Npr3 (91% identical), mouse Npr3 (91% identical), tropical clawed frog npr3 (68% identical), zebrafish npr3 (50% identical). Paralogues in human: GUCY2D (20% identical), GUCY2F (20% identical), ADCY7 (19% identical), ADCY4 (18% identical), NPR1 (18% identical), ADCY2 (18% identical), NPR2 (18% identical), ADCY3 (18% identical), ADCY1 (17% identical), ADCY8 (16% identical), ADCY6 (16% identical), ADCY5 (16% identical), and 5 more.
Diseases named in the same sentence as NPR3 in open-access papers:
NPR3 is named in the same sentence as 104 diseases in open-access papers, as found by Europe PMC text mining. Sharing a sentence is not in itself a finding about the gene and the disease. The quoted sentences say what the papers report.
Obesity (29 papers, 2011 to 2025). Accumulation of substantial excess body fat. "Genetic variations in NPR3 have also been associated with phenotypes such as blood pressure and obesity." (PMID 39132134, 2024). "Similar to lung ECs, kidney ECs showed a global downregulation of Npr3 in obesity, albeit to a lesser extent." (PMID 36400935, 2022). "An increased expression of NPR3 in WAT of obese patients was associated with lower levels of bioavailable NPs and consequently to a progression of obesity and typical concomitant diseases, such as diabetes, hypertension, and liver steatosis." (PMID 33206203, 2021). "Previous studies show that obesity also increases Npr3 levels in adipose tissue of mice and humans." (PMID 36993336, 2024). "Obesity-induced rats fed a high-fat diet have a lower NPR1/NPR3 ratio than the normal diet." (PMID 31817347, 2019). "In order to improve obesity, the NPR1/NPR3 ratio must be high in adipose tissue." (PMID 31817347, 2019). "The knockout of NPR3 in adipocytes, but not in skeletal muscle, resulted in a resistance to diet-induced obesity, increased energy expenditure, improved insulin sensitivity, increased glucose uptake, as well as protection from liver steatosis and visceral fat inflammation." (PMID 33206203, 2021). "Selected candidate genes Npr3 and Thbs1, as well as Gys2, a non-QTL gene that otherwise passed our enrichment criteria were characterised, revealing novel functional effects consistent with a contribution to obesity." (PMID 21915269, 2011).
Hypertension (16 papers, 2009 to 2025). The presence of chronic increased pressure in the systemic arterial system. "Other studies of genetic variants—reducing CNP/NPR3/Gi P/cAMP activity—reported increased incidence of circulatory disorders and high blood pressure." (PMID 36630163, 2023). "Single nucleotide polymorphism in Npr3 is associated with diastolic dysfunction, early onset of ischemic stroke, and hypertension." (PMID 28837672, 2017). "Recently, a study in 200,000 European descents also showed an association between rs1173771 in NPR3-C5orf23 with hypertension." (PMID 27191271, 2016). "In a case control candidate gene study that was focused on NPR3 polymorphisms and performed in a Chinese Han population, the G allele of rs2270915 was significantly associated with hypertension with an odds ratio of 1.55 (95% CI = 1.08–2.22)." (PMID 24465655, 2014). "Interestingly, four of these genes (KCNMB1, NEDD4L, ADD1 and NPR3) have been implied in genetic susceptibility for hypertension, while two genes have been associated with genetic susceptibility for stroke (PDE4D) or myocardial infarction (ADD1)." (PMID 19750006, 2009). "Several variations of NPR3 have been previously shown to be related to essential hypertension and coronary artery disease." (PMID 31948008, 2020). "Genetic variation in the promoter region of NPR3 has also been demonstrated by a candidate gene approach to be associated with alterations in ANP levels and hypertension." (PMID 24465655, 2014). "Most importantly, the presence of diastolic dysfunction in the homozygotes for this NPR3 genotype was independent of age, sex, BMI and hypertension with an odds ratio of 1.9 similar to that of hypertension, a well-known risk factor for diastolic dysfunction." (PMID 24465655, 2014).
colorectal cancer (8 papers, 2020 to 2025). A primary or metastatic malignant neoplasm that affects the colon or rectum. "The NPR3 gene has been implicated in the pathogenesis of clear cell renal carcinoma, osteosarcoma, colorectal cancer, and hepatocellular carcinoma." (PMID 38807601, 2024). "Upregulation of NPR3 promotes the proliferation of colorectal cancer cells and is associated with poor prognosis." (PMID 35558081, 2022). "In contrast, a study uncovered that NPR3 overexpression promoted the proliferation of colorectal cancer cells." (PMID 38807601, 2024). "NPR3 (natriuretic peptide receptor 3) has been reported as one of the prognostic markers for colorectal cancer (CRC), for which upregulation signified poor survival." (PMID 32899191, 2020). "CALB2 and C5orf23 (NPR3) are each involved in one clinical trial related to colorectal cancer." (PMID 39484215, 2024). "In addition, NPR3 upregulation could also promote the proliferation of colorectal cancer cells." (PMID 33602220, 2021). "In colorectal cancer cells, the effects of BC200 knockdown were analyzed by microarrays and identified natriuretic peptide receptor 3 (NPR3) as the gene whose mRNA expression was the most down-regulated." (PMID 32611613, 2020).
heart failure (8 papers, 2016 to 2025). Inability of the heart to pump blood at an adequate rate to meet tissue metabolic requirements. "We also identified a potential therapeutic target through the association of variants at the locus of NPR3 influencing diastolic function and risk of heart failure." (PMID 35479509, 2022). "The C-allele of the lead SNP (rs1173727) at this locus increases NPR3 expression, and is associated with increased blood pressure and LAVmaxi, and an increase in risk of heart failure." (PMID 35479509, 2022). "For CVD subtypes, similar MR associations for NPR3-predicted height were observed when considering the outcomes of coronary artery disease (0.75, 95% CI 0.60–0.92), stroke (0.69, 95% CI 0.50–0.95) and heart failure (0.77, 95% CI 0.58–1.02)." (PMID 37101178, 2023). "Our primary MR analyses support the effects of a reduced NPR3-mediated clearance function on reducing CVD risk, with analyses across CAD, stroke and heart failure producing similar MR estimates." (PMID 37101178, 2023). "Therefore, NPR3 mutation carrier may be at a previously unrecognized risk of heart failure." (PMID 27494651, 2016). "Using luciferase reporter and antagomir-based silencing assays, we demonstrated that the expression of NPR3 could be modulated by microRNA-143 (miR-143-3p), a microRNA species with up-regulated circulating concentrations in clinical heart failure." (PMID 29728596, 2018). "Notably, miR-100 was found to target NPR3 3′UTR and is differentially upregulated in the plasma of heart failure patients, suggesting a plausible microRNA-based compensatory mechanism in response to cardiac overload." (PMID 29728596, 2018). "The discovery of microRNA action on NPR3 is particularly interesting, considering that attenuation of the turnover rate of cardio-protective NPs in circulation underpins the development of next generation therapies, such as LCZ696, for heart failure and other cardiovascular diseases." (PMID 29728596, 2018).
clear cell renal cell carcinoma (6 papers, 2017 to 2024). "NPR3 was also reported to exert a tumour-suppressive effect by regulating MRCCAT1-mediated clear cell renal cell carcinoma metastasis." (PMID 37076508, 2023). "For example, MRCCAT1 promotes metastasis of clear cell renal cell carcinoma via inhibiting NPR3 and activating p38-MAPK signaling." (PMID 34906142, 2021). "Suppression of NPR3 expression facilitated the spread of clear cell renal carcinoma." (PMID 38807601, 2024). "NPR3 was proved to be inhibited by long non-coding RNA MRCCAT1 and further promoted the metastasis in clear cell renal cell carcinoma." (PMID 33304907, 2020).
myocardial infarction (6 papers, 2009 to 2023). Gross necrosis of the myocardium, as a result of interruption of the blood supply to the area, as in coronary thrombosis. "Previous investigations have demonstrated that the inhibition of Npr3 improves HF after myocardial infarction in mice, and that Htr4 was involved in the pathogenesis of ischemic HF in rats." (PMID 37762130, 2023). "The regulatory effect of miR-143 on NPR3 expression was further evidenced by the reciprocal relationship between miR-143 and NPR3 levels observed in hypoxia-treated human cardiac cells and in left ventricular tissue from rats undergoing experimental myocardial infarction." (PMID 29728596, 2018).
atrial fibrillation (5 papers, 2017 to 2025). A disorder characterized by an electrocardiographic finding of a supraventricular arrhythmia characterized by the replacement of consistent P waves by rapid oscillations or fibrillatory waves that vary in size, shape and timing and are accompanied by an irregular ventricular response. "Mice deficient in Npr3 exhibit prolonged SAN recovery time and increased atrial fibrillation susceptibility, indicating impaired SAN function." (PMID 38891063, 2024). "Mice lacking Npr3 display abnormal atrial fibrosis, leading to increased atrial fibrillation susceptibility and prolonged SAN recovery time." (PMID 38891063, 2024). "Additionally, the deletion of Npr3 in mice can lead to atrial fibrillation." (PMID 38891063, 2024). "Interestingly, a recent study using Npr3 (coding of NPRC) gene-knockout mice has indicated that NPRC, a non-guanylyl cyclase containing NP receptor prevents the progression of ANG II-dependent atrial fibrillation and remodeling." (PMID 32152395, 2020).
breast carcinoma (4 papers, 2020 to 2024). "PSME2, IL18 and NPR3 have been reported to have a close correlation with the proliferation, invasion, and migration of various tumors including breast cancer." (PMID 36092942, 2022). "Moreover, NPR3 was involved in constructing prognostic signatures to forecast the outcome of individuals with GC and breast cancer." (PMID 38807601, 2024). "Then, both univariate and multivariate logistic regression analyses demonstrated that 6 genes regulated by the RUNX family had a significant relationship with the prognosis of breast cancer patients, including PSME2, ULBP2, IL18, TSLP, NPR3, and TRDV1." (PMID 36092942, 2022). "The roles of other IRGs in our signature in breast cancer, including IGHE, SCG2, NPR3 and FABP6, require further clarification." (PMID 33216733, 2020).
cardiac hypertrophy (4 papers, 2018 to 2025). "In another set of experiments using isoproterenol-induced in vivo model of HF, intramyocardial administration of an Npr3 siRNA reduced cardiac hypertrophy and fibrosis, and elevated the levels of circulating A-type natriuretic peptide." (PMID 37762130, 2023). "While not yet linked to human HCM, NPR3 was upregulated in heart tissues of rat models with pressure-overload-induced cardiac hypertrophy." (PMID 40609041, 2025).
osteosarcoma (4 papers, 2021 to 2024). A usually aggressive malignant bone-forming mesenchymal neoplasm, predominantly affecting adolescents and young adults. "The expression of NPR3 inhibited the development of osteosarcoma by suppressing the PI3K-AKT pathway." (PMID 38807601, 2024). "NPR3 (natriuretic peptide receptor 3), could inhibit cancer cells growth in osteosarcoma via blocking the PI3K/AKT pathway." (PMID 34566519, 2021).
preeclampsia (3 papers, 2023 to 2025). Preeclampsia is a hypertensive disorder of pregnancy that is characterized by new-onset hypertension with proteinuria presenting after 20 weeks of gestation, and depending on mild or severe forms may initially present with severe headache, visual disturbances, and hyperreflexia. "Lastly, our method only captures the potential effects of NPR2 and NPR3 on preeclampsia risk that are related to the same signaling pathways affecting height." (PMID 40406480, 2025). "A 1-SD increase in NPR3-predicted height was associated with a 54% reduction in the odds of preeclampsia (OR 0.46, 95% confidence interval [CI] 0.30–0.69)." (PMID 40406480, 2025). "Given the roles of ANP and BNP in blood pressure regulation and their suggested associations to gestational hypertension, the observed effects of reduced NPR3 function on preeclampsia risk may also involve enhanced signaling by these peptides." (PMID 40406480, 2025). "Our results from the MR paradigm provide genetic evidence supporting the protective effect of CNP signaling through reduced NPR3 function in preeclampsia." (PMID 40406480, 2025). "Two-sample MR analyses were conducted to investigate the effects of NPR2 activation and NPR3 function on preeclampsia, utilizing the largest publicly available GWAS on preeclampsia, which included 296,824 female participants." (PMID 40406480, 2025).
Stroke (3 papers, 2009 to 2023). Sudden impairment of blood flow to a part of the brain due to occlusion or rupture of an artery to the brain. "Exploring cardiometabolic risk factors that may explain these effects, we find strong MR and colocalization evidence implicating NPR3 in the reduction of stroke risk, related to blood pressure lowering." (PMID 37101178, 2023). "Subsequent weighting of the MR analysis for SBP lowering effects suggested that this only partly explained the effects of NPR3 on reducing stroke risk, supporting that other NPR3-related mechanisms may also be at play." (PMID 37101178, 2023). "When investigating CVD subtypes, NPR3- and genome-wide predicted height negatively associated with CAD and stroke risk." (PMID 37101178, 2023). "At NPR3, a causal variant was shared between height and SBP (PPH4 = 0.80), height and DBP (PPH4 = 0.97), and height and stroke (PPH4 = 0.99)." (PMID 37101178, 2023). "For stroke, we found that the MR estimate for NPR3 was greater in magnitude than could be explained by a genetically predicted SBP effect alone." (PMID 37101178, 2023). "For stroke, however, the effect of NPR3-predicted SBP was greater than the effect of genome-wide predicted SBP; i.e., the NPR3-stroke effect was larger than what could be explained by a mediatory SBP effect alone." (PMID 37101178, 2023). "Although there was heterogeneity observed across MR estimates generated when considering different NPR3 variants related to height for the outcomes of CAD, stroke and SBP, this did not appear to translate to biased MR estimates." (PMID 37101178, 2023). "Finally, we did not observe meaningful differences between our main and sensitivity analysis-based MR estimates for the effect of NPR3 on CAD, HF, stroke, and SBP." (PMID 37101178, 2023).
arachnodactyly (2 papers, 2016 to 2021). "However, there are also important differences, which include: the occurrence of arachnodactyly in the Lgj, Lgj2J and Stri models; sacral/tail kinks in the Lgj, Lgj2J, Stri and Npr3 null mice; and premature death in Lgj2J and Npr3 null mice." (PMID 27959934, 2016).
breast tumor (2 papers, 2023 to 2024). "This phenomenon may be partially due to the fact that breast tumours are a highly heterogeneous entity with a high frequency of genetic mutations; genes related to NPR3 are upregulated in the BC TME and downregulated in other tumours." (PMID 37076508, 2023). "It was found that NPR3 actively stimulates the migration and proliferation of breast tumor cells." (PMID 38807601, 2024).
Cachexia (2 papers, 2019 to 2020). Severe weight loss, wasting of muscle, loss of appetite, and general debility related to a chronic disease. "Given the high and prompt reduction of musclin expression in muscle during C26-induced cachexia, we measured the expression of its receptor Npr3 and the related ones, Npr1 and 2 by Q-PCR." (PMID 31614775, 2019). "Similar results were obtained for Npr3-expressing plasmids, indicating that in C26-related cachexia, neither musclin nor its receptor becomes rate-limiting in atrophying TA." (PMID 31614775, 2019). "So, NP-driven myofiber-type shift could be beneficial during cachexia and exogenous musclin, but not Npr3, electroporation may promote it." (PMID 31614775, 2019).
colon cancer (2 papers, 2020 to 2024). "NPR3 was shown to be down-regulated upon KLF4 overexpression in a transfected colon cancer cell line." (PMID 38830769, 2024).
gastric cancer (2 papers, 2024 to 2025). A primary or metastatic malignant neoplasm involving the stomach. "We further explored the effect of NPR3 on epithelial-mesenchymal transition (EMT) in gastric cancer cells." (PMID 38807601, 2024). "Nevertheless, the specific function of NPR3 in gastric cancer has not been comprehensively examined." (PMID 38807601, 2024).
glomerular diseases (2 papers, 2024 to 2025). "In conclusion, this study suggests that pharmacologic blocking of NPR3 can be a possible strategy for the treatment of glomerular diseases." (PMID 38782980, 2024). "To explore whether targeting NPR3 could be a therapeutical option for glomerulopathies, we treated an NTS-induced mouse glomerulonephritis model with NPR3-specific blocking peptide (NPR3i)." (PMID 38782980, 2024).
hepatocellular carcinoma (2 papers, 2021 to 2024). A malignant tumor that arises from hepatocytes. "However, in hepatocellular carcinoma, FENDRR promoted cancer cells apoptosis by targeting miR-362-5p via stimulating NPR3 expression." (PMID 33602220, 2021).